NFE2L2 (NFE2 like bZIP transcription factor 2)
Diseases named in the same sentence as NFE2L2 in open-access papers (continued):
Sharing a sentence is not in itself a finding about the gene and the disease.
Stroke (17 papers, 2016 to 2025). Sudden impairment of blood flow to a part of the brain due to occlusion or rupture of an artery to the brain. "The greatest increase in Nfe2l2 gene expression occurred on day 3 after stroke in mice from the PT + βHB group." (PMID 38891898, 2024). "Previously, we showed that the expression of Nfe2l2 and a number of Nrf2-related genes increased in mice fed a ketogenic diet after stroke." (PMID 38891898, 2024). "Combined with the results, we speculate that Sancrs bind with Nfe2l2, then accelerate stroke and neurodegenerative processes." (PMID 33354572, 2020). "Flowchart illustrating the protective effect of zinc on stroke through various stages: GWAS analysis and NHANEs database, bioinformatic analysis, diagnostic model, pathway analysis showing autophagy, and genes involved (RELA, TNFSF10, NFE2L2, FADD, DDIT3, CFLAR)." (PMID 40969765, 2025). "The oxidative stress marker NFE2 Like BZIP Transcription Factor 2 (NFE2L2/NRF2) was examined next, as a measure of antioxidant protection in the stroke penumbra." (PMID 36533127, 2022). "CREBBP, NFE2L2 and PARP1 are known for their roles in the pathogenesis of stroke and post-stroke neurovascular remodeling and functional recovery." (PMID 34992531, 2021). "The key genes encompass critical pathways such as autophagy (e.g. NFE2L2, DDIT3, NAMPT), apoptosis (e.g. CFLAR, FADD) and NF-κB signaling (e.g. RELA, TNFSF10), suggesting a multifactorial involvement of these pathways in stroke pathophysiology." (PMID 40969765, 2025).
colitis (16 papers, 2008 to 2025). Inflammation of the colon. "Aronia berry consumption reduced the oxidative stress at least partly by preventing colitis-associated downregulation of Nfe2l2 and antioxidant enzymes in colon and MLN." (PMID 31212794, 2019). "CKMT1 knockout did not significantly impact the expressions of Nrf1, Ppara, Tfam, Tomm20, or Nfe2l2 during colitis." (PMID 40089459, 2025). "Rats received BER at low (25 mg/kg) and high (50 mg/kg) doses displayed marked upregulations (p < 0.05) in Nfe2l2 expression in respect to experimental colitis group." (PMID 33061833, 2020). "The mRNA expression of Nfe2l2 displayed significant downregulation (p < 0.05) in experimental colitis group in comparison with control group." (PMID 33061833, 2020). "In the spleen, Nfe2l2, Gclc, Gsr, Sod2, Gpx1, Gpx2, and Prdx1 were not consistently affected by T cell transfer colitis." (PMID 31212794, 2019).
colorectal cancer (16 papers, 2020 to 2025). A primary or metastatic malignant neoplasm that affects the colon or rectum. "Specifically, triptonide exhibited a binding energy of -9.62 kcal/mol with PGR, a core target of hypertensive retinopathy, while methyl ursolate showed a binding energy of -9.71 kcal/mol with NFE2L2, a core target of colorectal cancer." (PMID 41938594, 2025). "Data from colorectal cancer cell lines, human endothelial cells and even zebrafish models have revealed that NFE2L2 downregulation results in VEGFA repression and consequently, angiogenesis inhibition." (PMID 35806488, 2022). "NFE2L2 expression in pancreatic and colorectal carcinoma cell lines was comprised between 29%–58% with respect to the observed in Hs766T, thus the average percentage of expression in patients is significantly lower than the observed in sensitive cell lines." (PMID 33540681, 2021). "Our analysis using the UALCAN database, however, showed that CAT expression was more variable in pancreatic and colorectal carcinoma patients, while the NFE2L2 expression was very similar between the three types of tumors." (PMID 33540681, 2021). "A similar result was obtained in colorectal carcinoma patients, with one exception, where NFE2L2 expression was 61.36% ± 13.2% with respect to Hs766T expression." (PMID 33540681, 2021). "In colorectal cancer, genetic alterations of KEAP1 or NFE2L2 are rare (less than 2%)." (PMID 32992842, 2020). "In our meta-analysis, NFE2L2 is noticeable for the large discrepancy between positive correlation with LEF1 and negative correlation with TCF7L1, which clearly substantiates the importance of NFE2L2 as an important WNT/β-catenin target gene in human colorectal cancer." (PMID 32403323, 2020).
Hepatic steatosis (16 papers, 2018 to 2026). Steatosis is a term used to denote lipid accumulation within hepatocytes. "By contrast, the enhanced expression of NFE2L2 induced hepatic antioxidative and detoxification effects and decelerated the progression of hepatic steatosis in mice fed a methionine- and choline-deficient diet." (PMID 35052597, 2021). "In a study on hepatocyte-specific NFE2L2-upregulation mice with diet-inducing hepatic steatosis, thioredoxin-1, glutathione peroxidase-2, and Nqo1 were increased, and oxidative stress markers decreased." (PMID 35405942, 2022). "The protective role of overexpression of NFE2L2 against oxidative stress and reduced hepatic steatosis was demonstrated in mouse hepatic cells from a methionine–choline deficient (MCD) diet-induced NAFLD model." (PMID 35405942, 2022). "Additionally, vitamin D exhibited protective properties against high-fat diet (HFD)-induced fatty liver by promoting the nuclear translocation of the antioxidant molecule nuclear factor erythroid 2-related factor 2 (NFE2L2)." (PMID 38732118, 2024). "In a high-fat and high-fructose diet (HFHFr) mouse model, NFE2L2 was downregulated, while curcumin administration could reverse the abnormal serum biochemical parameters of hepatic steatosis." (PMID 35405942, 2022). "Supporting these findings, NF-κB1 sequencing informs liver function assessment, NFE2L2 activators counter hepatic lipotoxicity, and SERPINE1 serves as a biomarker in fatty liver disease and renal cancer progression." (PMID 41226722, 2025). "Additionally, we found unchanged BACE1 mRNA in vitro, but a reduced BACE1 protein expression in the livers of HFD mice, which might be due to increased Nrf2 (nuclear factor erythroid-derived 2-related factor 2, NFE2L2) activity under oxidative stress in hepatic steatosis." (PMID 39201455, 2024).
Insulin resistance (16 papers, 2021 to 2026). Increased resistance towards insulin, that is, diminished effectiveness of insulin in reducing blood glucose levels. "Notably, chronic exposure to environmental pollutants causes aberrant regulation of NFE2L2 gene and related antioxidant signaling, which can exacerbate selective susceptibility to brain insulin resistance under inflammatory conditions." (PMID 41516048, 2025). "We have shown that mitochondria- and NOX4-derived ROS drive NFE2L2 antioxidant defense in hepatocytes to limit the oxidative damage of macromolecules, the development of insulin resistance, and the progression to NASH and fibrosis." (PMID 38060313, 2023). "Another study showed that Nfe2l2-KO mice developed a phenotype with less insulin-resistance, and Nfe2l2-KO mice had higher plasma levels of fibroblast growth factor 21 (FGF21) and higher FGF21 mRNA levels in liver and WAT compared to WT mice." (PMID 35204118, 2022). "Meanwhile, homozygous minor alleles of NFE2L2 could also be more frequently found among women with insulin resistance, although the result was not statistically significant (p = .072)." (PMID 37768516, 2023). "Nfe2l2 deficiency in Lep(ob/ob) mice has been reported to reduce insulin-stimulated AKT1 phosphorylation along with a slight decrease in glucose transporter type 4 (GLUT4) expression, which reduced WAT mass and prevented hepatic lipid accumulation but induced insulin resistance and dyslipidemia." (PMID 35204118, 2022). "Previously we have shown that NFE2L2 drives Nox4 expression in muscle and, in turn, that NOX4-derived H2O2 enhances NFE2L2 antioxidant defense to attenuate muscle oxidative damage and insulin resistance." (PMID 38060313, 2023). "Therefore, we reasoned that ablating NOX4 and abrogating the resultant H2O2-dependent NFE2L2 antioxidant defense response, and, in particular, reducing SOD2, would promote mitochondrial oxidative stress to diminish insulin signaling and promote insulin resistance." (PMID 38060313, 2023).
head and neck cancer (15 papers, 2017 to 2024). A primary or metastatic malignant neoplasm affecting the head and neck. "NFE2L2 mutations have recently been shown to define subtypes with differential prognosis in lung and head and neck cancers." (PMID 33769711, 2021). "Specifically, for head and neck cancer, the expression levels of three genes, NFE2L2, RMND5A and SLC44A1, were associated with increased smoking-related mutational signature, while an inverse association was observed for one gene, ARRB1." (PMID 32928150, 2020). "Loss of exon 2 of NFE2L2 (Keap1 binding domain loss) was recently reported to be a new mechanism that also causes aberrant Nrf2 accumulation in the nucleus and promotes cell survival in lung, head and neck cancers." (PMID 31022969, 2019). "Inhibition of NFE2L2 by trigonelline reverses resistance to GPX4 inhibitor-induced ferroptosis in head and neck cancer cells, implicating NFE2L2 in the development of resistance to GPX4 inhibitors." (PMID 39534872, 2024). "Skipping of exon 2 and both exon 2 and 3 of NFE2L2 gene was shown to occur in lung and head and neck cancers to produce constitutively active Nrf2 forms resistant to Keap1-mediated degradation." (PMID 34063559, 2021). "Other notable examples are KEAP1 and NFE2L2/NRF2 mutations in NSCLC and head and neck cancers." (PMID 38549846, 2024). "We aimed to investigate if miRNAs hsa-miR-17-5p, hsa-miR-140-5p, and hsa-miR-874-3p could interfere in VEGFA, KRAS, and NFE2L2 expression in cell lines derived from head and neck cancer (HNC)." (PMID 35806488, 2022). "It has also been noted that intragenic deletions occur in NFE2L2 resulting in translation of NRF2 isoforms that lack amino acids that interact with KEAP1 in patients with squamous NSCLC and head and neck carcinoma." (PMID 33276631, 2020). "Deletion of NFE2L2 exon 2 represents an alternative mechanism for activation of NRF2 in a subset of squamous lung and head-and-neck cancers." (PMID 28767070, 2017).
pancreatic cancer (14 papers, 2013 to 2025). "Functionally, the loss of MGST1, similar to the loss of NFE2L2, reduces the resistance of pancreatic cancer cells to ferroptosis, making them more vulnerable to this form of cell death." (PMID 39534872, 2024). "The gene encoding for NRF2, NFE2L2, is rarely mutated in pancreatic cancer." (PMID 39337472, 2024). "Inducible MGST1 expression, mediated by the activation of the NFE2L2 pathway, inhibits ferroptosis in pancreatic cancer cells." (PMID 39534872, 2024). "NFE2L2 is a transcription factor up-regulated in the cell lines of pancreatic cancer, ductal adenocarcinoma and NSCLC." (PMID 23874428, 2013). "As KRAS and BRAF mutations are prevalent in CRC, NRF2 may frequently be upregulated by transcriptional activation of NFE2L2, as reported in mouse models of pancreatic cancer." (PMID 33276631, 2020). "In human pancreatic cancer cell lines, the expression of PIR is upregulated by NFE2L2 in response to ferroptosis-inducing agents (erastin or RSL3)." (PMID 39534872, 2024). "In our study, NFE2L2 overexpression significantly inhibits lipid peroxidation, Fe2+ ion levels, and GSH depletion induced by wogonin in pancreatic cancer cells." (PMID 36909174, 2023). "In pancreatic cancer cells, up-regulated SLC7A11-AS1 levels facilitate the stabilization of NFE2L2 and thereby reduce intracellular ROS." (PMID 35573800, 2022). "Moreover, the knockdown of NFE2L2 expression using siRNA significantly increases the lipid peroxidation, Fe2+ ion levels, and GSH depletion induced by wogonin in pancreatic cancer cells." (PMID 36909174, 2023).
type 2 diabetes (14 papers, 2015 to 2024). "The genetic variation at NFE2L2 has been associated with vascular function (forearm blood flow), autonomic function (heart rate variability), major vascular events and type 2 diabetes complications in cohorts and case control sets of adults." (PMID 36139799, 2022).
Cognitive impairment (13 papers, 2020 to 2026). Abnormal cognition is characterized by deficits in thinking, reasoning, or remembering. "Several groups have reported that genetically reducing NFE2L2 in animal models increases oxidative stress and inflammation, replicates gene alteration in gene expression typical of AD brains and exacerbates cognitive deficits." (PMID 36979483, 2023). "Cognitive impairments in 15-month-old mice correlated with a decrease in Bdnf expression in the hippocampus, Nfe2l2 expression, and an increase in the number of mtDNA damage in the cerebral cortex." (PMID 36499517, 2022). "The lack of NFE2L2 in 12-month-old APP/PS1 mice exacerbated cognitive deficits as we found a worsening of spatial learning and memory, working memory, and associative memory." (PMID 36979483, 2023).
metabolic syndrome (13 papers, 2020 to 2026). A cluster of metabolic risk factors for CARDIOVASCULAR DISEASES and TYPE 2 DIABETES MELLITUS. "What is the underlying factor responsible for alterations in markers associated with glucose dysmetabolism (GLP-1R), dyslipidemia (LDLRAP1), ferroptosis (NFE2L2), and autophagy (SQSTM1)?" (PMID 38915346, 2024).
periodontitis (13 papers, 2013 to 2026). An acute or chronic inflammatory process that affects the tissues that surround and support the teeth. "The nuclear factor erythroid 2-related factor 2 (NFE2L2 or NRF2)/Kelch-like ECH-Associated Protein 1 (KEAP1) (NRF2/KEAP1) signaling pathway plays a key role in periodontitis by modulating redox balance and inflammation of the periodontium." (PMID 39456522, 2024). "Chronic inflammation, oxidative stress, and NFE2L2 signaling failure in the periodontium are all potential causes of alveolar bone resorption, which can progress to periodontitis." (PMID 37215133, 2023). "Compared with T2DM patients with healthy periodontal conditions, T2DM patients with periodontitis exhibit significantly higher expression of ferroptosis-related genes, such as IL-1β, IL-6, NFE2L2, and ALOX5, in pancreatic tissue." (PMID 40541947, 2025). "The mRNA expression level of NFE2L2 was decreased in the periodontitis group and further decreased in the periodontitis with T2DM group." (PMID 36248844, 2022). "Among these genes NLRP3 and NFE2L2 related with periodontitis were reported." (PMID 37215133, 2023). "This could be important to overcome the downregulation of NFE2L2 observed in periodontitis." (PMID 35992149, 2022). "The qRT-PCR results revealed upregulation of IL-1β, IL-6 and ALOX5 in the periodontitis group and further upregulation in the periodontitis with T2DM group, while the expression of NFE2L2 was the opposite." (PMID 36248844, 2022). "Importantly, immunohistochemical validation revealed spatial expression patterns of both NFE2L2 and SLC25A3 in apical periodontitis lesions." (PMID 40909264, 2025). "Among these, four CRGs were found to be down-regulated in chronic apical periodontitis (CAP), namely Nuclear Factor Erythroid 2-Related Factor 2 (NFE2L2), Dihydrolipoamide S-Succinyltransferase (DLST), Solute Carrier Family 25 Member (SLC25A3), and Glycine Cleavage H Protein (GCSH)." (PMID 40909264, 2025).
squamous cell carcinoma (13 papers, 2014 to 2024). A carcinoma arising from squamous epithelial cells. "Somatic mutations in the coding region of NFE2L2 occur especially in patients with a history of smoking or suffering from squamous cell carcinoma and contribute to poor treatment prognosis." (PMID 35056649, 2022). "The prevalence of mutations in either KEAP1 or NFE2L2 (the gene encoding NRF2) is approximately 30% overall in NSCLC, with KEAP1 mutations occurring primarily in adenocarcinoma and NFE2L2 in squamous cell carcinoma." (PMID 33920029, 2021). "They found novel somatic mutations in the MAPK1 gene (8%), HLA-B gene (9%), EP300 (16%), FBXW7 (15%), NFE2L2 (4%), and ERBB2 (6%) of 79 squamous carcinomas, and ELF3 (13%) and CBFB (8%) mutations in 24 adenocarcinomas." (PMID 26701206, 2016). "Indeed, activating mutations in NFE2L2 have recently been discovered to commonly co-occur with PIK3CA amplification and mutation in multiple squamous-cell carcinomas including lung, and cooccurrence contributed to greater sensitivity to knockout of either gene in cell lines." (PMID 35872531, 2022).